IL18 (interleukin 18)
Diseases named in the same sentence as IL18 in open-access papers (continued):
Sharing a sentence is not in itself a finding about the gene and the disease.
colon carcinoma (38 papers, 2006 to 2025). "In this study, we confirmed that IL-18 expression was decreased in primary colon cancer tissues and this low expression was associated with T stage (P = 0.001) and AJCC stage (P = 0.013) as well as the OS rates." (PMID 33294056, 2020). "Our data suggest that the decreased expression of IL-18 in colon cancer was associated with prognosis and tumor proliferation." (PMID 33294056, 2020). "We then assessed the association between the OS rates and DFS rates of colon cancer patients and IL-18 expression." (PMID 33294056, 2020). "Our findings imply that IL-18 is implicated as a potential prognostic indicator and therapeutic target in colon cancer." (PMID 33294056, 2020). "The data revealed that low IL-18 expression in colon cancer tissues was associated with tumor size and AJCC stage and implicated that IL-18 is a prognostic factor for OS." (PMID 33294056, 2020). "Meanwhile, IL-18 silencing in NLRP6 deficient mice has been associated with increased colon cancer development, indicating the pivotal role of cytokines in mediating the anti-carcinogenic activities of NLRP6." (PMID 27206676, 2016). "The expression of IL-18 is reported to be low in colon cancer tissues and may be associated with tumor size, while also suppressing the proliferation of colon cancer." (PMID 37176567, 2023). "They found that symbiotic fungi can activate inflammasomes and promote the maturation of IL-18, which in turn prevents colonic inflammation and colon cancer while also mediating anti-tumor T-cell responses." (PMID 37943609, 2023). "NLRP3 inflammasome has previously been shown to mediate the production of IL-18, which increases the tumoricidal activity of natural killer cells against metastatic colon tumor cells in mouse liver." (PMID 37833249, 2023). "In AOM/DSS-induced colon cancer, it has been shown that IL-18 levels were decreased in tumor-bearing mice, that the NLRP3/ASC/CASP1/IL-18 axis was important to dampen tumor growth and this was dependent on IFN-γ production." (PMID 37298187, 2023). "In summary, we showed that two L. lactis strains, IBB109 and IBB417, exhibit potent a proliferation inhibition and increased interleukin 18 (IL-18) expression in human colon cancer cells (Caco-2)." (PMID 35694291, 2022). "Inflammasomes have been reportedly activated by NLRP3-ASC-caspase-1, promoting the expression of the downstream factors IL-18 and IL-1β and playing an anti-tumor role in colon cancer." (PMID 35309942, 2022). "A previous study in metastasized colonic tumor indicated that IL18 secretion mediated by NLRP3 was able to induce tumoricidal activities of NK cells against metastatic colon cancer cells in the liver of mouse." (PMID 36276158, 2022). "The expression of IL-18 has been previously investigated in several types of cancer, including gastric and colon carcinomas." (PMID 33507690, 2021). "By contrast, LFA-1 and ICAM-1 upregulated by IL-18 can facilitate the eosinophil-mediated tumoricidal activity against a colon carcinoma cell line." (PMID 33336008, 2020). "The effects of orally administered probiotics on basic cancer and immune parameters and cytokine concentration (TNF-α, IL-1β, IL-18) in colon tumours were studied." (PMID 32168834, 2020). "Here, we explored the expression of IL-18 in colon cancer tissues and analyzed the correlation between the expression and the prognosis of patients." (PMID 33294056, 2020). "Taking these observations into account, we evaluated the effect of IL-18 on colon cancer cell proliferation." (PMID 33294056, 2020). "By upregulating the expression of IL-18 with plasmid, we investigated the functional relevance of IL-18 on cellular proliferation in colon cancer cell." (PMID 33294056, 2020). "In in silico analyses of TCGA colon cancer cohort, data also confirmed that patients with low IL-18 expression had a lower 10-year survival rate than patients with high IL-18 expression (P = 0.00028)." (PMID 33294056, 2020).
colon carcinoma (continued). "To explore the clinicopathologic significance of IL-18 expression, we used IHC to detect the expression of IL-18 in tissues from 116 cases of primary colon cancer." (PMID 33294056, 2020). "In clinical analyses, mRNA and protein expressions of IL-18 were decreased in tissues of colon cancer patients." (PMID 33294056, 2020). "Likewise, overt inflammation and lack of IL-18 in the Nlrp6−/− mice has been associated with increased colonic tumor development, however, as seen for Nlrp3−/− mice it is still unknown whether administration of IL-18 is capable of rescuing the susceptibility phenotype." (PMID 25071785, 2014). "Furthermore, the production of IL‐18, which is mediated by the Nlrp3 inflammasome, has the potential to suppress the growth of colon tumors effectively." (PMID 41025546, 2025). "Moreover, the high expression of IL18 in APC-MUT colon cancer patients predicted good prognosis in the WCH cohort (log-rank test, p = 0.028)." (PMID 36934880, 2023). "However, during the malignant transformation, the ovarian and colon cancer cells lose the ability to process IL-18 as a result of the defective Caspase-1 activation." (PMID 34114949, 2021). "We found that the expression of IL-18 was significantly decreased in colon cancer tissues." (PMID 33294056, 2020). "To explore the possible roles of IL-18 in development of colon cancer, we first analyzed the TCGA database and found that IL-18 was significantly lower in colon cancer tissues than normal tissues, and this downregulated expression was happened on the early stage of the disease." (PMID 33294056, 2020). "Our study uncovers that IL-18 is involved in the progression and proliferation of colon cancer." (PMID 33294056, 2020). "IL-18 may be considered a novel tumor suppressor and a potential therapeutic target for colon cancer patients." (PMID 33294056, 2020). "Above results indicate that IL-18 is correlated with colon cancer growth and progression." (PMID 33294056, 2020). "The present study was designed to investigate the expression and function of IL-18 in colon cancer." (PMID 33294056, 2020). "Our study has identified that IL-18 may act as a colon cancer suppressor that inhibit the proliferation of colon cancer cells." (PMID 33294056, 2020). "Additionally, NLRP6 protein levels and IL-18 production were increased by SCFAs but decreased by NLRP6 siRNAs in murine CT26 colon carcinoma cells." (PMID 31255176, 2019). "Moreover, we showed that colon cancer cellular proliferation may be potently dampened by the overexpression of IL-18 expression." (PMID 33294056, 2020). "However, the expression and the role of IL-18 in colon cancer tissue remain less understood." (PMID 33294056, 2020). "Moreover, upregulation of IL-18 inhibited colon cancer cell proliferation." (PMID 33294056, 2020). "Furthermore, our results indicate that IL-18 markedly represses colon cancer cell proliferation." (PMID 33294056, 2020). "Among 23 paired colon cancer cases that were assessed for expression of IL-18 mRNA, 13 (56.5%, P < 0.01) adjacent noncancerous tissues showed a more than 2-fold increase compared with tumor tissues." (PMID 33294056, 2020). "However, ablation of GSDMD in sporadic colon tumors did not result in altered IL-1α, IL-1β, and IL-18 as well as NLRP3 or ASC speck formation." (PMID 38898209, 2024). "Likewise, western blot analyses confirmed a significant downregulation of IL-18 protein in colon cancer tissues compared with adjacent noncancerous tissues." (PMID 33294056, 2020). "However, it is not known whether colonic cancer cells retain a functional caspase-1/IL18 pathway that could be activated and able to modulate the Th1/Tc1 response of TILs." (PMID 33430344, 2021). "We found that the number of colonic tumors and the size of B16-OVA tumors in IL-37 absent and present mice when injected with IL-18-blocking antibodies was not significantly differences." (PMID 35046386, 2022).
acute respiratory distress syndrome (36 papers, 2011 to 2026). Progressive and life-threatening pulmonary distress in the absence of an underlying pulmonary condition, usually following major trauma or surgery. "Tetracycline also reduced IL-1ß and IL-18 production by alveolar leukocytes in patients with direct acute respiratory distress syndrome." (PMID 39475317, 2024). "IL-18, a proinflammatory mediator and member of the IL-1 cytokine family, is critical in pulmonary diseases, such as acute respiratory distress syndrome (ARDS) and chronic obstructive lung disease (COPD)." (PMID 32676490, 2020). "Pro-inflammatory interleukins like IL-1β, IL-6, IL-2, IL-17 and IL-18 are critically involved in cytokine storm, hyperinflammation, and acute respiratory distress syndrome, whereas anti-inflammatory cytokines like IL-10 contribute to immune regulation and resolution of inflammation." (PMID 41683812, 2026). "In humans, IL18 plasma concentration levels are elevated in acute respiratory distress syndrome." (PMID 30990817, 2019). "The predictive value of elevated IL-18 levels in critically ill patients was assessed in a nested case-control study within the Acute Respiratory Distress Syndrome Network trial (median urine IL-18 was 104 pg/mL at 24 hours in the AKI group versus 0 pg/mL in the group without AKI)." (PMID 22131986, 2011). "Acute respiratory distress syndrome (ARDS) is yet another devastating pathology in which IL-18 is a player." (PMID 39769266, 2024). "The binding of SARS-CoV-2’s spike protein to ACE2 leads to dysregulation, contributing to acute respiratory distress syndrome (ARDS), hypertension, and the overproduction of cytokines such as IL-1β, IL-17A, and IL-18." (PMID 40003732, 2025). "However, IL-18 is known to be elevated in patients with acute respiratory distress syndrome (ARDS) resulting from influenza virus infections." (PMID 37398192, 2023). "Moreover, increased levels of IL-18 are observed with increased mortality in sepsis-induced acute respiratory distress syndrome (ARDS)." (PMID 37445927, 2023). "A nested case–control study, which was performed within the Acute Respiratory Distress Syndrome (ARDS) Network trial, found that urine IL-18 values 24 h before the development of AKI enabled the prediction of AKI development after the adjustment for baseline and clinical characteristics." (PMID 32557377, 2020). "In particular, in a study of critically-ill adult patients with acute respiratory distress syndrome (ARDS), increased urinary IL-18 was found to be an early marker of AKI, preceding changes in serum creatinine by 1–2 days, and was also an independent predictor of death." (PMID 28624882, 2018). "Acute lung injury/acute respiratory distress syndrome (ALI/ARDS) is also associated with an overwhelming inflammatory response: proinflammatory cytokines IL-1β and IL-18 levels are high in bronchoalveolar lavage fluid from patients with ALI/ARDS and correlate with mortality." (PMID 28740332, 2017). "Urinary IL-18 has been studied by Parikh and coworkers in a variety of clinical settings, including delayed graft function, cardiac surgery, acute respiratory distress syndrome, and cross-sectionally in patients with and without kidney disease." (PMID 22518072, 2012).
liver disease (36 papers, 2014 to 2025). "The activation of the NLRP3 inflammasome and the release of downstream IL-1β and IL-18 have been shown to be associated with the pathogenesis of various liver diseases." (PMID 30105078, 2018). "This section highlights recent advancements in the understanding of the molecular and cellular mechanisms of liver diseases associated with IL-1 family cytokines, particularly focusing on IL-1, IL-33, and IL-18." (PMID 26549942, 2015). "Current researches have demonstrated that TNF, IL-1α/β, IL-1Ra, IL-6, IL-18, IL-33, IL-36, IL38, CCL2 and CCR2 are closely associated with liver disorders." (PMID 41333471, 2025). "Given the close relationship between NLRP3 inflammasome, IL-1β, and IL-18 and their pivotal roles in the progression of liver diseases through the recruitment of inflammatory cells, we assessed the expression of NLRP3 inflammasome." (PMID 39949920, 2025). "Serum IL18 concentrations were related to the severity of Child-Pugh liver disease in cirrhotic patients." (PMID 37317244, 2023). "TNF-α, IL-1β, IL-6, and IL-18 are often used as markers of inflammatory responses and are involved in the induction of liver diseases." (PMID 36865438, 2023). "IL-18 levels in serum of PBC patients are significantly elevated compared to those in healthy controls or patients with other liver diseases and increased with disease progression, suggesting that IL-18 is strongly associated with the progression of PBC." (PMID 35300072, 2022). "The proinflammatory cytokines IL-6 and IL-18 have critical roles in establishment of inflammation, and involved in the induction of liver diseases." (PMID 36311675, 2022). "So far, multiple genes have been shown to be associated with increased liver disease risk, such as CTLA-4, IL-18, transmembrane 6 superfamily member 2 and GSTM1." (PMID 34886817, 2021). "We established a highly sensitive IL‐18‐TRFIA method that successfully detected serum IL‐18 concentrations in different liver diseases." (PMID 33720453, 2021). "Comparison of the serum IL‐18 concentrations between five groups of liver disease patients and healthy controls." (PMID 33720453, 2021). "In our study, the clinical indicators of ALT, LD, DBIL, TP, AST, and GT of 5 liver diseases were significantly positively correlated with IL‐18." (PMID 33720453, 2021). "The concentration of IL‐18 in each of the five liver diseases is different, which provides a new detection index for clinical diagnosis." (PMID 33720453, 2021). "Concerning the hepatic disease, IL-18 also has immunological and clinical implications on CHC, as affected patients often exhibit significantly elevated values of this mediator, compared to healthy controls." (PMID 34840527, 2021). "We found that the IL‐18 serum concentration of patients with various liver diseases differed compared to the healthy controls." (PMID 33720453, 2021). "Inflammasome triggers or amplify liver diseases by releasing pro-inflammatory cytokines such as IL-1β, IL-1α, IL-18, and also through other inflammatory mediators such as High Mobility Group Box 1 (HMGB1)." (PMID 32431709, 2020). "Previously, increased Interleukin (IL)-18 was observed in both biliary duct disease and liver disease." (PMID 30340555, 2018). "Being a paradigmatic experimental model of ALI, current knowledge on ill-fated properties of IL-18 in APAP intoxication likewise emphasizes the potential of this cytokine to serve as therapeutic target in other entities of inflammatory liver diseases." (PMID 29472923, 2018). "Colonization by intestinal Prevotella leads to changes in the metabolism of the microbiome, reducing the production of IL-18, which increases gut inflammation and may be relevant to liver disease." (PMID 40241734, 2025). "In liver disease, innate immune cells respond to hepatic insults by activating cell-intrinsic inflammasomes via toll-like receptors and NF-κB, and by releasing pro-inflammatory cytokines (such as IL-1β, IL-18, TNF-α and IL-6)." (PMID 38908436, 2024).
liver disease (continued). "The negative correlation with key inflammatory cytokines, notably those involved in acute and chronic inflammatory responses and liver diseases, like IL-1β, IL-18, and TNF-α, reinforces the hypothesis that CR1L might have a protective role in AH." (PMID 38573776, 2024). "Although further studies are needed to elucidate how IL18 can augment hepatocyte apoptosis, our data are consistent with the idea that hepatocyte-derived IL18 should be regarded as a new player in the pathogenesis of inflammatory liver diseases." (PMID 37461687, 2023). "Importantly, we observed a significant positive correlation between TIM‐3 and IL‐18 concentration in the serum of patients with liver disease (r = 0.275, p < 0.01)." (PMID 33720453, 2021). "We have tried to apply the concept of trained immunity to liver diseases, based on the role of the members of the IL-1 superfamily, first of all IL-1β but also IL-18 and IL-33, in modulating innate lymphoid immunity carried by natural killer cells, innate lymphoid cells or innate T-αβ lymphocytes." (PMID 31507607, 2019). "Besides being an inflammatory NF-κB-activating cytokine, two exceptional characteristics are key to the function of IL-18 in liver diseases." (PMID 29472923, 2018). "In this review, we will focus on the roles of IL-1, IL-18, and IL-33 in various liver diseases, following a brief introduction to the IL-1 family, with the aim of clarifying the molecular and cellular networks involving each cytokine that are activated in liver diseases." (PMID 26549942, 2015). "The IL‐18 and IL‐21 levels were significantly higher in patients with AIH than in those with other liver diseases and autoimmune disorders." (PMID 37397575, 2023). "Chronic HCV infection is associated with elevated plasma levels of systemic markers of immune activation such as sCD14, sCD163, IL-18, Mac-2BP, ATX, and IP-10, more so in patients with advanced liver disease." (PMID 35482664, 2022). "The decrease in IL-18 is consistent with a previous rat study on RBAC and d-Ga1N-induced liver disease, which showed that RBAC suppressed a model of hepatitis by at least partially downregulating IL-18." (PMID 29853945, 2018). "Elevated levels of IL18 have been observed in plasma and liver tissue of patients with cholestatic disorders, further supporting the involvement of the NLRP3 inflammasome in liver disease." (PMID 40089787, 2025). "IL-18 exerts pleiotropic effects on hepatic NK cells, priming FasL-mediated cytotoxicity, and interferon-γ (IFN-γ)-dependent responses to prevent the development of liver diseases." (PMID 30319645, 2018). "In our experiments, histological and serological examination revealed that S. mansoni infection induced normal hepatic disorders upon IL-18KO mice (data not shown), suggesting that IL-18 itself plays only a minor role in the etiology of schistosomiasis." (PMID 24824897, 2014). "Thus, the ability to produce IL-18 in response to HCV replication could modulate the level of necroinflammatory activity in the liver, and the progression of liver disease, as has been previously proposed." (PMID 32575428, 2020). "Thus, IL-18 might contribute to the development of liver disease, albeit the origin of IL-18 may not be solely from adipose." (PMID 25512222, 2014). "When comparing patients with clinically significant portal hypertension (CSPH, HVPG ≥ 10 mmHg) to patients without CSPH, there were significantly enhanced serum levels of IL-6 and IL-18 in the former group." (PMID 38077228, 2023). "IL-18 is a pro-inflammatory cytokine frequently elevated in chronic viral infections (such as HCV infection) and in liver disease (regardless of etiology)." (PMID 35482664, 2022). "CD40L upregulation was mediated both by E. coli presented by MR1 as well as IL-12 and IL-18, providing a mechanism through which MAIT cells could drive bile duct damage in inflammatory liver disease in the absence of infection, in a non-specific manner." (PMID 26743076, 2016).